CD4 (CD4 molecule)
Diseases named in the same sentence as CD4 in open-access papers (continued):
Sharing a sentence is not in itself a finding about the gene and the disease.
gastric cancer (continued). "explored the differences of immune infiltration cells in gastric cancer and they found that activated CD4+ memory T cells and Tfh are related to worse overall survival and progression‐free survival, while that naive B cells are the reverse for progression‐free survival." (PMID 38652109, 2024). "Relationship between CD4 and clinicopathologic features in patients with advanced gastric cancer." (PMID 38549936, 2024). "Also, the intratumoral CD4+FOXP3+ T-cells in gastric cancer (GC) engage with nearby immune effector cells, exerting their antitumor effects indirectly rather than through direct contact with tumor cells." (PMID 38339311, 2024). "Moreover, integrin β5 expression was positively correlated with the infiltration levels of CD4+ T cells, macrophages, and dendritic cells, particularly where lower macrophage infiltration led to improved prognosis in gastric cancer." (PMID 38312516, 2024). "The novel combination of CD3+/CD4+ cells with myosteatosis emerged as a highly effective indicator, offering heightened predictive efficacy for identifying recurrence and metastasis in post‐surgery gastric cancer patients." (PMID 38894548, 2024). "Bioinformatic analysis has shown that ghrelin can alter the infiltration levels of immune cells such as B cells, CD8+ T cells, and CD4+ T cells, and macrophages in gastric cancer tissues, thereby modulating the tumor’s immune microenvironment and promoting the progression of gastric cancer cells." (PMID 38275675, 2024). "Also, the infiltration of CD4+ T cells is higher in patients with T3 stage of GC compared to that in T1 and T2 stage, implying a critical effect of CD4+ T cells in the prognosis of gastric cancer." (PMID 38748299, 2024). "In addition, the CCL14 protein in the TILs of gastric cancer tissues was related to Lauren’s type cells, T cells (CD4+ and CD8+), and CD68+ macrophages in the TME." (PMID 38887558, 2024). "Besides, COL5A2 is a prognostic biomarker in gastric cancer, highlighting its correlation with immune infiltrates, such as CD4+ and CD8 + T cells, macrophages and plasmacytoid dendritic cells." (PMID 38789829, 2024). "In addition, CD4+ and CD8+ T cells are closely associated with an improved response to immunotherapy in patients with advanced gastric cancer." (PMID 37342362, 2023). "Interestingly, a combination of CLDN18.2-negative status with high levels of CD4 + T cells or CD8 + T cells is predictive of better prognosis in gastric cancer." (PMID 37582713, 2023). "Similarly, in gastric cancer, higher expression of FAM83H was significantly associated with decreased infiltration of B cells, CD4+ helper T cells, CD8+ T cells, macrophages, and myeloid dendritic cells." (PMID 37761326, 2023). "Additionally, lncRNAs, including A2M-AS1, C2orf27A, and ZNF667-AS1, impaired activation of CD4+ T cells and affected prognosis of gastric cancer patients." (PMID 37696973, 2023). "Memory PD-1+CD8+ T cells and PD-1+CD8+T/PD-1+CD4+T cell ratio might be effective for screening benefit population of immunotherapy in advanced gastric cancer patients based on this preliminary evidence." (PMID 37974194, 2023). "The pre-treatment CD4+/CD8+ TILs ratio by immunohistochemistry on gastric cancer tissues revealed a remarkable correlation with lymphovascular invasion, TNM stage and response to neoadjuvant chemotherapy, and lower CD4+/CD8+ TILs ratio predicted significantly better survival outcomes." (PMID 37974194, 2023). "Besides gastric cancer, disproportionate CD4+ over CD8+ T cell ratios have also been observed in CRC." (PMID 36550535, 2022). "Additionally, LAYN is associated with the levels of immune infiltration (CD8+ T cells, CD4+ T cells, macrophages and neutrophils) as well as patient prognosis in various cancers, especially colon cancer and gastric cancer." (PMID 35676936, 2022). "In addition, Bregs promote CD4+CD25- effector T cells conversion into CD4+FoxP3+ Tregs by producing TGF-β1 in gastric cancer." (PMID 36618354, 2022).
gastric cancer (continued). "CD4+ memory T cells were significantly increased in patients treated with antiprogrammed death-1 (PD-1) antibody blockade and their increased abundance in the tumor microenvironment predicted a benign prognosis for patients with gastric cancer." (PMID 36578802, 2022). "ICOS+ Foxp3+ CD4+ T cells were abundantly observed in the late stages of gastric cancer." (PMID 35311157, 2022). "Furthermore, in advanced gastric cancer, a higher ratio of LAG3+CD4+/CD4+ T cells and LAG3+CD8+/CD8+ T cells is associated with better prognosis, although, at the invasive tumor margin, higher LAG3 expression is associated with better prognosis." (PMID 35111155, 2021). "Higher infiltration of CD4+ lymphocytes is also related to favorable prognosis in gastric cancer." (PMID 33793095, 2021). "In gastric cancer, M1 macrophages, CD8+ T cells, and activated natural killer (NK) cells were associated with an increased probability of response, while resting CD4+ T cells, naïve CD4+ T cells, naïve B cells and activated mast cells were correlated with a decreased probability of response." (PMID 34220837, 2021). "Also, high RS was significantly associated with increased stromal and immune scores and increased infiltration of CD4+ T cell, CD8+ T cell, cancer-associated fibroblast, and macrophage in gastric cancer tissues." (PMID 34746312, 2021). "Therefore, the roles of CD4+ TILs are unclear and further investigation is needed for gastric cancer with peritoneal metastasis." (PMID 33793095, 2021). "In gastric cancer, the study on effector memory CD4 T cell-related chemokines remains very limited." (PMID 33426088, 2020). "CD8+ T and FOXP3+CD4+ T cells were important markers for diagnosis of gastric cancer." (PMID 33135337, 2020). "Additionally, patients with well‐differentiated gastric carcinoma had higher levels of CD4 + T cells." (PMID 31631566, 2019). "Interestingly, in a model of gastric cancer, tumor cells induced CD4+ T-cells to secrete CCL5, which in turn, induced apoptosis in CD8+ T cells, while neutralization of CCL5 with monoclonal antibodies induced tumor suppression." (PMID 29559701, 2018). "T cell immunity is important in tumor response, and there are many subsets of T cells which played different roles in gastric cancer, CD4+ T cell, including regulatory T cells, CD8+ T cell, CD45RO+ memory T cells, and other molecules related to T cell immunity." (PMID 29682534, 2018). "Related meta-analysis had shown that DC-CIK could increase the CD3+ T cells, CD3+ CD4+ T cells, and the ratio of CD4+/CD8+ T cells in peripheral blood of patients with hepatocellular carcinoma (HCC) or gastric cancer." (PMID 30648123, 2018). "These Bregs positively correlated with the levels of CD4+Foxp3+ Tregs in gastric cancer." (PMID 28470464, 2017). "We next explored the regulatory properties of Bregs on CD4+Th cells in gastric cancer." (PMID 26378021, 2015). "Moreover, Bregs play a significant immunosuppressive role in gastric cancer, not only by inhibiting CD4+Th cell cytokine production, but also by converting CD4+CD25− effector T cells to CD4+FoxP3+Tregs in a TGF-β1- dependent way." (PMID 26378021, 2015). "In this study, we showed that, in contrast to peripheral-derived γδ T cells directly isolated from PBMCs of gastric cancer patients, tumor-activated γδ T cells not only killed tumor cells efficiently but also strongly induced primary CD4+ and CD8+ αβ T cells proliferation and differentiation." (PMID 24741609, 2014). "We found that RORγ and IL-17A, the main Th17 factors, are highly upregulated in gastric mucosa derived from both H. pylori infection and gastric cancer suggesting a link between H. pylori infection, the inflammatory CD4+ T cell phenotype, Th17, and gastric cancer." (PMID 23365642, 2013).
gastric cancer (continued). "Moreover, the study aims to amalgamate CD3+/CD4+ cells with severe myosteatosis to formulate a novel and more comprehensive prognostic index with the intent of accurately appraising the recurrence and progression risks in gastric cancer patients." (PMID 38894548, 2024). "Furthermore, a multifactorial regression analysis of 376 advanced osteosarcoma patients found that the CD4+/CD8+ is an independent prognostic factor for osteosarcoma.PDGFD played a regulatory role in gastric cancer and pancreatic cancer by interfering with the tumor microenvironment." (PMID 38652223, 2024). "We found that the expression ofC1GALT1 was positively correlated with the levels of infiltrating of CD4+ T cells and macrophages in gastric cancer, indicating that C1GALT1 may govern crosstalk with macrophages and cytotoxic T lymphocytes, which was consistent with those findings in a previous study." (PMID 38807485, 2024). "Nevertheless, these findings may suggest the certain influences of SLC35A2 on the infiltration of immune cells in the immune microenvironment through some potential pathway in gastric cancer, including CD4+ T cell activation and macrophage polarization, which requires further work to confirm." (PMID 37467193, 2023). "Little is known on how metabolic reprogramming potentially prompts transition of activated and resting CD4+ memory T cells infiltration in tumor microenvironment of gastric cancer (GC)." (PMID 38090588, 2023). "In this study, immune infiltration analysis showed that resting CD4 memory T cells, activated CD4 memory T cells, monocytes, M0 macrophages, M1 macrophages, M2 macrophages, activated mast cells and neutrophils exhibited high levels of infiltration in gastric cancer tissues." (PMID 36936437, 2023). "Notably, exploring this aspect may put a direction for further studies to explore the potential mechanism of CD4+ T cells for these mental and cognitive issues in elderly gastric cancer patients." (PMID 36386524, 2022). "Moreover, Bregs were highly enriched in tumor tissue and peripheral blood of gastric cancer and could suppress the proliferation of autologous CD4+ T cells." (PMID 36339942, 2022). "Furthermore, it has also been shown that increased CD4 T cells producing IL22 in tumor tissues are associated with tumor progression and poor prognosis of patients, which is consistent with our results in advanced (T3, T4 phase) gastric cancer." (PMID 33426088, 2020). "Meanwhile, KLHL5 was closely related with level of CD8+ T cells (cor = 0.237, P = 4.19e−06), CD4+ T cells (cor = 0.459, P = 4.19e−06), and macrophage (cor = 0.534, P = 1.22e−28), neutrophil (cor = 0.297, P = 5.1e−09), and dendritic cell (cor = 0.469, P = 9.48e−22) infiltration in gastric cancer." (PMID 33363208, 2020). "Notably, a study conducted on mouse models of gastric carcinoma showed that high concentrations of melatonin were able to alter the regulatory T lymphocytes (T-reg), a subtype of CD4+ lymphocytes which are identified as CD4+CD25+ cells, being involved in tumoral cell escape from the immune system." (PMID 33167396, 2020). "Therefore, we can conclude that STAT3 might be able to pass through membrane structures between gastric cancer stem cells and Treg/CD4+ uncommitted T cells to change the shift them to Th17 cells." (PMID 31024835, 2019). "There is little knowledge about impacts of inhibitory molecules with cytokine on tumor-infiltrating CD4+ T-cells in the presence of gastric cancer (GC)." (PMID 29213216, 2017). "Here, our data confirms CD163 in gastric cancer has a positive correlation with Tregs (CD4, CD25 and FOXP3), MDSCs (CD33, CD11b and CD14) and Cafs (FAP), indicating CD163 level is an potential index to monitor the status of tumor associated macrophages, Tregs, MDSCs and Cafs in gastric cancer." (PMID 29152078, 2017).
gastric cancer (continued). "However, numerous cycles of chemotherapy may lead to a reduction in the immune functions of the patients with gastric cancer, with decreased ratios of CD4+ and CD4+/CD8+ cells, reduced NK cell activities and an increased proportion of CD8+ cells." (PMID 24137296, 2013). "Gastric cancer patients with high SII (p = 0.003) and low CD4+ T cell (p = 0.007), B cell (p = 0.001), and NK cell counts (p = 0.001) had shorter survival times." (PMID 41873119, 2026). "Gastric cancer tissues had reduced CD3+T, CD3+CD4+T cells and M1 macrophage infiltration, increased M2 macrophages and CD14+monocytes; AKAP12 was positively correlated with monocytes." (PMID 41798945, 2026). "Our findings further demonstrate that IL-31 derived from FAP+CAFs promotes the polarization of naive CD4+ T cells toward the Th2 phenotype, thereby establishing an immunosuppressive TME and facilitating gastric cancer immune evasion." (PMID 40843362, 2025). "The discharge of enhancers and altered activation of GPR35 leads to the growth and movement of gastric cancer cells, a notable reduction in certain immune cells (CD8 + T cells and CD4 + memory T cells), and/or infiltration (T‐cells and macrophages)." (PMID 40736072, 2025). "In cases of gastric cancer, there was a positive correlation between SIRT1 and CD4+ T cells (r = 0.166), CD8+ T cells (r = 0.295), macrophages (r = 0.285), and neutrophils (r = 0.218)." (PMID 41020376, 2025). "In the subgroup analysis for predicting the prognosis of intestinal type gastric cancer, it was shown that PDL1, CD4, MSI-H were closely related to gastric cancer DFS, while PDL1, CD4+TILs, CD8+TILs were closely related to gastric cancer OS." (PMID 40636693, 2025). "For instance, in gastric cancer, SDC2 + CAFs exhibit increased cross-talk with neighbouring CD4 + /CD8 + T cells and NK cells, establishing immunosuppressive signalling pathways, and stromal SDC2 correlates with advanced stage and poor prognosis." (PMID 40715090, 2025). "Tα1 increased the percentage of CD4+CD25+Foxp3+ (suppressive antitumor-specific Tregs), Tregs, IL-1β, TNF-α, and IL-6 in patients with gastric carcinoma." (PMID 40599771, 2025). "In laparoscopic gastric cancer surgery, TEAS was found to increase levels of CD3+ and CD4+ cells and improve the CD4+/CD8+ ratio, while decreasing CD8+ cell levels." (PMID 39465871, 2024). "CD19+CD24hiCD38hi cells in gastric cancer are the primary source of IL-10 and can significantly inhibit the secretion of IFN-γ and TNF-α by CD4+ T cells." (PMID 39840050, 2024). "Lymphocyte subsets, including CD3+/CD4+ cells, CD4+/CD8+ ratio and CD19+ cells, are indicative of clinical prognosis in gastric cancer surgery patients." (PMID 38894548, 2024). "The findings established CD3+/CD4+ cell–myosteatosis as an independent prognostic factor for both PFS and OS in patients who underwent radical gastric cancer surgery." (PMID 38894548, 2024). "Since data for esophageal cancer, gastric cancer, and colon cancer are only available in the BBJ database, we verified “CD45 on CD4+” and “CD28 on CD39+ activated Treg” only." (PMID 38533503, 2024). "We further accessed the expression of B cells, CD4+ T cells, CD8+ T cells, macrophages, neutrophils, and immune checkpoints (CTLA4, LAG3, PD-1, and PD-L1) in gastric cancer tissues using IHC and mIHC staining and multispectral image analysis." (PMID 38887558, 2024). "In this investigation, we created four ML models utilizing DCE-MRI data and assessed and compared their efficacy in quantifying the numbers of tumor-infiltrating T cells, including CD3, CD4, and CD8 subsets, in advanced gastric cancer patients." (PMID 38549936, 2024). "In gastric cancer patients with FLOT chemotherapy (5-Fluorouracil, Leucovorin, Oxaliplatin and Docetaxel), CD4+/CD8+ lymphocyte ratio was elevated and predicted favourable therapy response." (PMID 37696973, 2023).
gastric cancer (continued). "Here, we established an activated CD4+ memory T cells-related 3-gene prognostic model (BATF2, MYB and CD36) in gastric cancer to evaluate the activation status of CD4+ memory T cells." (PMID 37781029, 2023). "In a gastric cancer model, tumor-infiltrating CD8 T cells exhibited both cytotoxic and exhausted phenotypes, while CD4 T cells were mainly regulatory T cells." (PMID 38067255, 2023). "In patients with gastric cancer, acupuncture compound general anesthesia reduced the negative impacts on immune function based on obviously decreased levels of CD3+, CD4+ and CD4+/CD8+ after subtotal gastrectomy." (PMID 36865562, 2023). "Understanding the expression and differences in CD4+ and CD8+ TILs in patients with advanced gastric cancer can help identify patients, provide reasonable and personalized treatment, and contribute to the advancement of precision medicine." (PMID 37342362, 2023). "Univariate logistic regression analysis found that CD3D, CD8, CD4, age, family history, tumor location, tumor size, grade of differentiation and TNM stage were all prognostic factors for gastric cancer." (PMID 35719985, 2022). "In addition, ferroptosis is involved in regulating CD4+ T-cell activation in gastric cancer (GC), correlated with prognosis, and these findings provide a novel idea for GC immunotherapy and hold promise for future clinical application." (PMID 36267413, 2022). "At the cellular level, patients with gastric cancer have decreased numbers of CD3+ and CD8+ cells and an increase in CD4+, CD19+, CD44+, CD25+, and NK compared to a disease-free control." (PMID 34862564, 2022). "The pearson correlation coefficients between CD3D expression and CD3, CD4, CD8 and PD-L1 expression in gastric cancer." (PMID 35719985, 2022). "In gastric cancer patients, we found that the expression of CD3D was highly positively correlated with the expression of CD3, CD4, CD8, and PD-L1." (PMID 35719985, 2022). "Since CD3D was positively correlated with the expression of CD3, CD4, CD8 and PD-L1, the effect of CD3D in combination with these factors on the prognosis of gastric cancer was analyzed." (PMID 35719985, 2022). "In our study, we found that CD4 and CD8 were good prognostic factors for gastric cancer in both univariate and multivariate analyses." (PMID 35719985, 2022). "ZNF521 expression was correlated with levels of infiltrating CD4+ and CD8+ T cells, macrophages, neutrophils, and DCs in bladder cancer, lung squamous cell carcinoma, and gastric cancer, and was also correlated with diverse immune markers." (PMID 36311294, 2022). "The expression of ZNF521 was correlated with infiltrating levels of CD4+ T and CD8+ T cells, macrophages, neutrophils, and dendritic cells in gastric cancer, which also correlated with diverse immune marker sets." (PMID 36311294, 2022). "Then, immunohistochemical staining of CD3D, CD3, CD4, CD8 and PD-L1 was conducted to investigate the expression of CD3D in gastric cancer and the correlation between the expression of CD3D and tumor infiltrating lymphocytes (TILs) and PD-L1." (PMID 35719985, 2022). "Although the exact mechanism of the altered proportions of CCR4+/CD3+ and central memory CD4+ cells in the gastric mucosa of patients with cancer is unknown, focusing on lymphocytes in the gastric mucosa might help improve our understanding of gastric cancer development after H. pylori eradication." (PMID 36569708, 2022). "Meanwhile, the poorer prognosis may be associated with the abnormally high expression of three immune cells (resting memory CD4+ T cells, regulatory T cells and monocytes) and down expression of two immune cells (M1 macrophages and resting NK cells), especially in Asian males with gastric cancer." (PMID 35778697, 2022). "In our analysis, the levels of CD4+ T cell and FOXP3+ Treg infiltration were significantly higher in patients with T3 gastric cancer than patients with T1 and T2 gastric cancer." (PMID 34421887, 2021).